KIT (KIT proto-oncogene, receptor tyrosine kinase)
Diseases named in the same sentence as KIT in open-access papers (continued):
Sharing a sentence is not in itself a finding about the gene and the disease.
pancreatic cancer (20 papers, 2006 to 2025). "KIT is a proto-oncogene associated with several tumours that enhances proliferation and invasion of pancreatic cancer cell lines; KITLG/SCF and TPSAB1 are mast cell markers indicating an early infiltration of stroma surrounding PanINs with mast cells." (PMID 23372777, 2013). "Taken together, the results show that miR-221-3p may act as an underlying tumour marker for prognosis prediction in pancreatic cancer and may work by acting on KIT, CDKN1B, RUNX2, and BCL2L11 expression." (PMID 32943991, 2020). "In KIT-positive pancreatic cancer cell lines, 5 μM imatinib mesylate significantly inhibited SCF-enhanced proliferation to the level shown by nonstimulated control." (PMID 17044945, 2006). "With regard to expression of SCF, pancreatic cancer specimens were evaluated for simultaneous expression with KIT." (PMID 17044945, 2006). "Our results demonstrated that the SCF-KIT pathway enhanced the proliferation and invasiveness in KIT-positive pancreatic cancer cell lines and that the enhanced proliferation and invasion were inhibited by imatinib mesylate." (PMID 17044945, 2006). "KIT was expressed in 38% of pancreatic cancer patients and expression correlated with the degree of venous system invasion." (PMID 17044945, 2006). "On the other hand, two other studies from the same department reported that about 80% of pancreatic cancers expressed KIT." (PMID 17044945, 2006). "In vitro, we demonstrated that the SCF-KIT pathway enhanced the proliferation and invasiveness in KIT-positive pancreatic cancer cell lines and that the enhanced proliferation and invasion were inhibited by imatinib mesylate." (PMID 17044945, 2006). "Concerning pancreatic cancer, two studies reported that KIT-positive patients had a tendency toward lower survival than did c-kit-negative patients, but the differences were not significant." (PMID 17044945, 2006). "Namely, the invasive ability of KIT-positive pancreatic cancer cell lines was significantly enhanced by addition of SCF at concentrations above 1 ng/mL." (PMID 17044945, 2006). "In the present study, KIT was expressed in 38% of pancreatic cancer specimens (16 of 42 patients) by immunohistochemistry." (PMID 17044945, 2006). "In KIT-positive pancreatic cancer cell lines, proliferation and invasion were significantly enhanced by addition of SCF." (PMID 17044945, 2006). "We propose that inhibitors of c-kit tyrosine kinase receptor have the potential to slow the progression of KIT-positive pancreatic cancers." (PMID 17044945, 2006). "Of note, other PDGFR and c-KIT inhibitors may also have potent antitumor activity in pancreatic cancer." (PMID 40076604, 2025). "While the existing knowledge on pancreatic cancer is limited, certain studies have suggested that KIT may serve as a valuable prognostic marker for favorable outcomes in specific solid tumors." (PMID 39123462, 2024). "Therefore, our studies suggested that PDGFRα and KIT downregulation in pancreatic cancer leads to decreased p70S6K phosphorylation at Ser 418, and increased IRS-1 phosphorylation at Ser 636 via increased PI3K/AKT mTOR/P70S6K signaling." (PMID 27014871, 2016). "Pancreatic cancer cells expressed KIT in 16 of the 42 cases (38.1%)." (PMID 17044945, 2006). "From these facts, we suppose that KIT induced VEGF expression may have relationship with venous system invasion in pancreatic cancer." (PMID 17044945, 2006). "For KIT-positive pancreatic cancers, KIT inhibitors could block the ligand-dependent signaling pathway." (PMID 17044945, 2006). "Based on those results, we defined these two pancreatic cancer cell lines as KIT-positive." (PMID 17044945, 2006). "Pancreatic cancer cells expressed SCF in fourteen KIT-positive specimens." (PMID 17044945, 2006). "We asked whether imatinib mesylate might inhibit KIT-stimulated proliferative and invasive activities of the two KIT-positive pancreatic cancer cell lines (PANC-1 and SW1990)." (PMID 17044945, 2006).
pancreatic cancer (continued). "Our studies indicate that KIT expression by pancreatic cancer cells may have functional significance." (PMID 17044945, 2006). "Previous studies showed that mutations in the c-KIT or platelet-derived growth factor receptor (PDGFR) drive ligand-independent constitutive kinase activity and downstream signaling, resulting in increased proliferation, migration, and survival of pancreatic cancer cells." (PMID 40076604, 2025). "In addition, we examined the hub genes KIT, CDKN1B, RUNX2, and BCL2L11, which may act in pancreatic cancer, and confirmed that the expression of KIT, CDKN1B, RUNX2, and BCL2L11 is indeed affected by miR-221-3p." (PMID 32943991, 2020). "Thus, miR-221-3p may affect the incidence and development of pancreatic cancer by affecting KIT, CDKN1B, RUNX2, and BCL2L11 expression." (PMID 32943991, 2020). "Thus, we propose that serum SCF and SCF secreted from mast cells could contribute to in vivo tumor progression of KIT-positive pancreatic cancer." (PMID 17044945, 2006). "Thus, we propose that a KIT inhibitor could be used with gemcitabine, or used as a second choice when the pancreatic cancer is resistant to gemcitabine." (PMID 17044945, 2006). "Thereafter, we determined the KIT protein levels in various GIST cell lines (GIST-T1, GIST-430, GIST-430/654, and GIST-48B), HEK-293T, and various pancreatic cancer cell lines (BXPC-3, MIAPACA-2, PANC-1, and PATU8988T)." (PMID 40963922, 2025). "The result of the PPI network projected four genes (KIT, CDKN1B, RUNX2, and BCL2L11) as hub genes in pancreatic cancer, which may be possible targets of miR-221-3p." (PMID 32943991, 2020). "Finally, we also analyzed KIT and SCF expression in pancreatic cancer tissues using immunohistochemistry and correlated the results with clinical features." (PMID 17044945, 2006). "In addition, we analyzed the relationship between KIT and SCF expression in pancreatic cancer tissues and examined clinical features and prognosis." (PMID 17044945, 2006). "In the report which concluded that 6.1% of pancreatic cancer expressed KIT, antigen retrieval was not performed." (PMID 17044945, 2006). "In our immunohistochemical study, 14 pancreatic cancer specimens co-expressed KIT and SCF, and the proportion of SCF-positive specimens was significantly larger in KIT-positive specimens than in KIT-negative ones." (PMID 17044945, 2006).
small cell lung carcinoma (20 papers, 2005 to 2025). Small cell lung cancer (SCLC) is a highly aggressive malignant neoplasm, accounting for 10-15% of lung cancer cases, characterized byrapid growth, and early metastasis. "Despite the efficacy of imatinib in GIST with imatinib-sensitive activating KIT mutations, tyrosine kinase inhibitors have been disappointing in small cell carcinoma of the lung (SCCL), 28-88% of which are reported to be KIT+." (PMID 23285214, 2012). "MP-470 was recently reported to produce a limited response in a refractory GIST patient with KIT mutations and to show antitumour activity when combined with standard-of-care chemotherapy in neuroendocrine tumours, NSCLC, and small cell lung cancer (SCLC)." (PMID 31684958, 2019). "Coexpression of c-KIT and its ligand in small-cell lung cancer, for example, appears to result in an autocrine growth loop sustaining tumor cell proliferation." (PMID 22839358, 2012). "As to prognosis, in small-cell lung cancer, patients with KIT expression had a significant tendency toward lower survival than did KIT-negative patients." (PMID 17044945, 2006). "Further, c-KIT and its ligand, SCF, are known to be expressed preferentially in small cell lung cancers." (PMID 35681762, 2022). "Co-expression of KIT and SCF has been reported in small-cell lung cancer, and in those diseases, autocrine pathways are suggested." (PMID 17044945, 2006). "The transmembrane protein c-kit is a receptor tyrosine kinase (KIT) and KIT is expressed in solid tumors and hematological malignancies such as gastrointestinal stromal tumor (GIST), small-cell lung cancer and chronic myelogenous leukemia (CML)." (PMID 17044945, 2006).
diabetes (19 papers, 2010 to 2026). "We further found that loss of miR-10b-5p in KIT+ β cells and ICC in Kit-mir-10b KO mice led to diabetes and GI dysmotility, revealing a novel miR-10b-KLF11-KIT pathway that regulates glucose homeostasis and GI motility." (PMID 38396943, 2024). "Imatinib exhibited broad systemic effects, with strong associations to cardiovascular (hypertension), metabolic (diabetes), and neuropsychiatric (schizophrenia and depression) conditions, consistent with its multi-kinase inhibition profile, targeting PDGFR and c-KIT." (PMID 40732226, 2025). "miR‐10b‐5p targets KLF11, which in turn regulates KIT expression and improves GID in diabetes and post‐diabetes." (PMID 37218372, 2023).
dysgerminoma (18 papers, 2007 to 2024). A malignant germ cell tumor characterized by the presence of a monotonous primitive germ cell population. "Second, screening for KIT mutations is imperative to reduce the risk of dysgerminoma in Turner syndrome, especially for patients with Y mosaicism who are recommended for hormone replacement therapy." (PMID 38283145, 2024). "According to the most recent research, about one-third of dysgerminomas are found to have KIT mutations, and these cases are more likely to be in an advanced stage at the original diagnosis." (PMID 37372675, 2023). "Among mOGCTs, mutations in KIT have been previously identified exclusively in dysgerminoma (DG) at frequencies of 27% (6 of 22) and 24% (4 of 17), whereas no mutations have been reported in tumors of patients with pure or mixed histologies of IT and YST." (PMID 33435376, 2021). "Significantly, the pathogenic KIT gene variant, D816A, was identified in both the dysgerminoma and BM samples in this case." (PMID 33246418, 2020). "In one patient (case 16) showing GB and mainly dysgerminoma, missense mutations in c-KIT were found in exon 9 and 17, resulting in N505I and D820E respectively, which were not present in normal adjacent adnexal material." (PMID 22937135, 2012). "Activating mutations in KIT are present in a significant minority of patients with dysgerminoma and are associated with high-level expression of KIT protein in the tumor cells." (PMID 20069115, 2010). "KIT was mutated in codon 816 in 5/14 unilateral dysgerminomas, whereas all dysgerminomas from bilateral cases (n = 4) showed a wild type sequence, as did all OGCTs of other histotypes (n = 22)." (PMID 17274819, 2007). "We detected five KIT mutations in the same codon, but found three different base changes in five OGCTs (four pure dysgerminomas and one dysgerminoma with gonadoblastoma)." (PMID 17274819, 2007). "The high expression of KIT in dysgerminoma prompted us to investigate the possibility of a gene mutation." (PMID 17274819, 2007). "For dysgerminomas that have the mutation, KIT is a potential therapeutic target." (PMID 37372675, 2023). "Based on the present results, it is not possible to determine whether the initial driving event in the dysgerminoma corresponds to the somatic KIT variant or LOI at 15q." (PMID 37575996, 2023). "Finally, variant calling in the dysgerminoma detected a somatic pathogenic activating KIT mutation (NM_000222.3:c.1676T>G) with a variant allele frequency of 20%." (PMID 37575996, 2023). "c-KIT is the most useful diagnostic marker for human dysgerminoma." (PMID 31547830, 2019). "In one case of combined dysgerminoma/gonadoblastoma we detected a KIT mutation." (PMID 17274819, 2007). "However, KIT was mutated in 5/13 unilateral dysgerminomas, whereas all bilateral dysgerminomas (n = 4) and all other histological types (n = 22) showed a wild type sequence." (PMID 17274819, 2007). "Furthermore, PGCs expressing pluripotent genes, such as NANOG and POU5F1, and which express complete demethylation, gain additional genomic abnormalities, such as the KIT mutation, or the isochromosome 12p; subsequently, this causes the emergence of dysgerminomas (DGs)." (PMID 37296950, 2023). "In DSD, presence of Y-chromosomal material leads to the gonadal dysgenesis, in which the germ cells survive because of prolonged expression of both OCT3/4 and TSPY, setting the stage for GB and subsequent dysgerminoma development; although in a minority of cases mutations in c-KIT might play a role." (PMID 22937135, 2012). "Tumor identity was confirmed, while genetic analyses detected a somatic pathogenic activating KIT mutation and LOI at the PWS locus in the dysgerminoma." (PMID 37575996, 2023). "KIT mutations in OGCT subtypes, such as dysgerminomas, gonadoblastomas, and yolk sac tumors, are most frequently exhibited in exon 17; these mutations can lead to increased chances of survival and the proliferation of undifferentiated oogonia." (PMID 37296950, 2023).
dysgerminoma (continued). "In the current case, the immunohistochemical expression of c-KIT in germ cells and α-inhibin in sex cord-stromal cells supports the histological diagnoses of GB and dysgerminoma." (PMID 31547830, 2019). "Immunohistochemical study revealed moderate immunoreactivity for c-KIT in germ cells of GB and dysgerminoma elements, whereas the Sertoli/granulosa-like cells of GB were strongly immunoreactive for α-inhibin." (PMID 31547830, 2019). "A mutation in c-KIT codon 816 in a DSD patient presenting with GB and dysgerminoma has also been reported previously, indicating that in rare cases these mutations can be found in DSD patients." (PMID 22937135, 2012). "In accordance with these reports, we found KIT expressed in 80–100% of neoplastic cells in dysgerminomas and gonadoblastomas, and in 15% of yolk sac tumours." (PMID 17274819, 2007). "Eighty-two percent of the dysgerminomas had abnormalities on chromosome 12p, which were not linked to KIT mutations." (PMID 37372675, 2023). "A possible alternative hypothesis therefore is that the dysgerminoma and ASM originated from a common cancer stem cell harboring the KIT D816A mutation and developed independently." (PMID 33246418, 2020). "KIT gene amplification was not evident by quantitative PCR, suggesting that the normal allele had been deleted in the dysgerminoma cells." (PMID 33246418, 2020). "The germ cells of gonadoblastoma and dysgerminoma components were immunoreactive for c-KIT." (PMID 31547830, 2019). "KIT protein can also be present in dysgerminomas without an identifiable KIT mutation; the mechanism underlying KIT overexpression in these cases is not known." (PMID 20069115, 2010). "We expect this mechanism not to be limited to KIT, but demonstrate that mutations in KIT are responsible for a sizeable number (5/17) of cases containing dysgerminoma." (PMID 17274819, 2007). "BM examination of the osteolytic lesions revealed multifocal, dense infiltrates of mast cells that showed positive immunohistochemical staining for mast cell tryptase, CD25, CD33, and c-KIT, but no dysgerminoma cell was observed." (PMID 33246418, 2020). "If mutations in c-KIT or PDGFRA play a significant role in the development of GB and the development of dysgerminoma in DSD patients is not clear so far because of the lack of multiple studies." (PMID 22937135, 2012). "Thus, the presence of the KIT D816A variant in both the ASM and dysgerminoma cells in our present patient is unlikely to be a coincidence." (PMID 33246418, 2020). "The activated c-KIT, together with prolonged expression of OCT3/4 may allow increased survival and proliferation of undifferentiated gonocytes/oogonia, leading to the development of dysgerminoma." (PMID 22937135, 2012). "Expression of the stem cell-related markers OCT-3/4 and KIT were present in 80% of dysgerminomas, 75–100% of tumours containing gonadoblastoma and in two yolk sac tumours, whereas NANOG and AP-2γ were present in approximately half of the dysgerminomas and gonadoblastomas." (PMID 17274819, 2007).
mast cell disease (18 papers, 2004 to 2026). "In the current study, we investigate the biological relevance of loss of TET2 in the context of KIT D816V associated mast-cell disease both in vivo in a mouse model and in vitro in human cells." (PMID 24788138, 2014). "None of the other related clinical manifestations of inherited GIST (dysphagia, hyperpigmentation, urticaria pigmentosa) associated with germline KIT mutations was seen in patients with PDGFRA mutations." (PMID 23036227, 2012). "Lastly, mast cell diseases show point mutations of the KIT gene (D816V) in 95% of cases." (PMID 30251956, 2019). "In addition, KIT D816V mutation with a variant allele frequency (VAF) ≥ 10% in the peripheral blood or bone marrow leukocytes is useful as it may indicate high mast cell disease burden, with possible multilineage involvement (B-findings)." (PMID 35884535, 2022). "New drugs mainly directed against the tyrosine kinase activity of KIT have dramatically changed the quality of life and prognosis of mast cell diseases." (PMID 31824655, 2019). "Altogether, our data show that MITF and MITF-dependent targets may be therapeutic to target mast cell release abilities and survival in KIT oncogenic mast cell diseases." (PMID 36834926, 2023). "This suggests the specific KIT exon 11 mutation may be required for the feature of urticaria pigmentosa whereas development of GIST may be a more generalized phenomenon, associated with a broad spectrum of KIT activating germline mutations." (PMID 23036227, 2012). "Thus, imatinib usually is ineffective in controlling KIT-D816V-positive mast cell disease." (PMID 28438191, 2017). "A predisposition to GIST was present in these families but not hyperpigmentation or urticaria pigmentosa, providing further support to the fact that specific KIT germline mutations may lead to variable clinical phenotypes." (PMID 23036227, 2012). "Pharmacologically targeting c-KIT provides a golden opportunity to investigate the differential effects of these compounds in AD, PD, ALS, and frontotemporal dementia (FTD), as well as mast cell disease with c-KIT mutations (mastocystosis) and without (psoriasis and urticaria) c-KIT mutations." (PMID 39221072, 2024).